EGF (epidermal growth factor)
Diseases named in the same sentence as EGF in open-access papers (continued):
Sharing a sentence is not in itself a finding about the gene and the disease.
cancer (continued). "However, it was also indicated that the formation of ACFs was more related to a suppressed apoptosis of cancer cells by way of modulating the epidermal growth factor (EGF) signaling pathway rather than the phosphorylated Akt and Erk." (PMID 24224098, 2013). "Since all carcinoma cell lines we examined migrated well even when EGF was not added, we examined the effect of B56γ1 overexpression on migration of Calu1 cells in the presence and absence of EGF." (PMID 23704935, 2013). "An additional property of cancer stem cells (CSCs) is the ability to grow as non-adherent spheres when cultured in serum-free medium supplemented with basic fibroblast growth factor (bFGF) and epidermal growth factor (EGF)." (PMID 23095512, 2012). "The present study focuses on the development and the in vitro evaluation of a radiolabeled MNT possessing epidermal growth factor (EGF) as the ligand module, which ultimately might be suitable for targeting the many types of cancers overexpressing EGF receptors (EGFR)." (PMID 23107475, 2012). "To assess whether the 72 amino acid MUC1 cytoplasmic domain (MUC1.CD) would localize to the nucleus of carcinoma cells in the absence of EGF, we expressed MUC1.CD fused to GFP and monitored the cells for MUC1 localization." (PMID 22586492, 2012). "The fact that EGF inhibitors reduced EMT induction while PMN-MDSC purified from RETAAD tumors did not produce EGF may suggest that PMN-MDSC stimulate EGF production by the cancer cells." (PMID 21980263, 2011). "Additionally, actin polymerization does not occur in quiescent invadopodial precursors of carcinoma cells suggesting that the filaments are capped and following epidermal growth factor stimulation actin incorporation occurs in a single but extended peak." (PMID 21339827, 2011). "HT-29 epithelial cancer cells were treated with 10 combinations of saturating or subsaturating concentrations of TNF, EGF and insulin (0, 0.2, 5, 100 ng/ml TNF and 0, 1, 100 ng/ml EGF or 0, 1, 5, 500 ng/ml insulin respectively), which collectively represent all the cues used in the study." (PMID 17559646, 2007). "In carcinoma cell lines, the major trends included a strong STAT3 activation by LIF (ADLC, H125), an increased (ADLC, H23) or decreased STAT3 activation by IL-6 (H125, H324), a decreased ERK activation by EGF (H522), and a treatment-independent, constitutive activation of the ERK pathway (H23)." (PMID 16271139, 2005). "Epidermal growth factor (EGF), which is highly expressed in several types of cancer cells, including OSCC, was found to be among the top three genes positively correlated with MFI2, so the activation of EGF signaling might play a critical role in OSCC carcinogenesis." (PMID 37309001, 2023). "The study found that due to their small size (12~15 kDa), the natural “immune” nanobody could easily be formatted after binding to EGF, quickly passed through the blood, and only had a short residence time at the target, which is not suitable for cancer treatment." (PMID 36835588, 2023). "However, EGF-dependent signaling pathways also negatively regulate autophagy by activating the class I PI-3 kinase, which is a major upstream activator of mTORC1, and indeed, EGFR inhibition leads to an enhancement of autophagy in certain types of cancer cells." (PMID 36206843, 2022). "Furthermore, cisplatin treatment of CAFs caused a negative association of colony area with BIRC5 and EGF, and a positive association of colony area with NANOG expression in cancer cells treated by CMCAF_post-cisplatin medium, which was not seen in CMCAF cocultured cells." (PMID 33671869, 2021). "Moreover, growing data show that the modulatory actions of platelet factors such as EGF (epidermal growth factor), IGF-I (insulin-growth factor-I), TGF-β (transforming growth factor beta), PDGF and VEGF (vascular endothelial growth factor) alter the cancer chemotherapy sensitivity or resistance." (PMID 32164265, 2020).
cancer (continued). "Moreover, the activation of EGFR and Ras signaling pathways was previously well known to promote cell proliferation and survival of certain tumors, so we further clarified that neither EGF nor cytokines induced senescence in cancer cell lines under our experimental conditions." (PMID 32323422, 2020). "Intrinsically, our studies indicated that EGF-induced de novo Grb7 tyrosine phosphorylation/activation is essential for the tumorigenicity, suggesting that expression and activation of both Grb7 and EGFR might collaboratively function as a critical point in cancer developmental processes." (PMID 31083325, 2019). "However, these paradoxical roles of EGF in cancer progression have still not been evaluated." (PMID 30845713, 2019). "Moreover, treatment with EGF, which is an inducer of Erk1/2 phosphorylation, promoted clonal formation in both HSP60 KD and metformin-treated Panc-1 cells, findings that support Erk1/2 phosphorylation has a role in HSP60 KD-related and metformin-induced cancer cell growth inhibition." (PMID 29415987, 2018). "Moreover, substantial evidence validates the cross-talk among RTKs, including epidermal growth factor (EGF), basic fibroblast growth factor (bFGF), vascular endothelial growth factor (VEGF), and platelet-derived growth factor (PDGF) receptors, and their aberrant signaling in cancer." (PMID 28545562, 2017). "In addition, we demonstrated that EGF show different functionality than NGF or GDNF and that EGF is a new potential analgesic modulator in the process of pain sensitization, a result of importance not least in the light of the increased use EGFR blockers for therapeutic cancer treatment." (PMID 21187008, 2010). "EAI045 did not affect EGF-mediated pAkt in WT-expressing WM983B cells, suggesting that there is no side effect on normal tissue and organ in cancer patients." (PMID 40649937, 2025). "CAFs arise through similar mechanisms to myofibroblasts in IPF, including EMT and EndMT, driven by cytokines such as TGF-β, epidermal growth factor (EGF), VEGF, FGF, TNF-α, interleukin 1β (IL-1β), and IL-6 secreted by cancer and non-malignant stromal cells." (PMID 40862703, 2025). "In contrast, KI exposure did not affect EGF transcript levels; however, it did reduce EGFR1 expression (here referred to as EGFR) in cultured murine WR21 cancer cells." (PMID 40508009, 2025). "Some signaling communication networks (CD46, HSPG, EGF, CEACAM, PDGF, and EDN) exclusively involved high PAK2-expressing cancer cells, with no participation from low PAK2-expressing cancer cells." (PMID 38343537, 2024). "JWG-071 potently inhibited EGF-induced ERK5 phosphorylation in the three cancer cell lines tested (active ERK5 auto-phosphorylates, resulting in a slower migrating band), without affecting EGF-induced ERK1/2 phosphorylation." (PMID 36123565, 2022). "In this cancer cells, EGFR is activated without EGF stimulation when they are cultured in growth medium, perhaps due to high level of EGFR expression, and we have shown that TSP1‐CD148 interaction suppresses this EGFR activity." (PMID 34791835, 2022). "We cultured the cancer organoids, termed P009T and P013T, as well as normal colon organoids, termed NCO, in medium containing Wnt, R‐Spondin, and EGF (WRE medium) or alternatively in medium lacking Wnt and R‐Spondin (E medium)." (PMID 34409732, 2021). "The epidermal growth factor (EGF) is one of the most common inducer of migration of normal and cancer cells." (PMID 32575572, 2020). "Some WTAP-related pathways have been proposed such as EGF signaling, the mTOR pathway or the WT1-TBL1 axis, while the involvement of WTAP as an m6A regulator in human cancers has not been explored previously." (PMID 31438961, 2019). "Although this study demonstrates that the β2-ARs are not involved in prevention of EGF-mediated JB6 P+ cell transformation, the study does not indicate that β-ARs do not play a role in preventing cancer." (PMID 31107911, 2019).
cancer (continued). "Thus, our findings have not only revealed previously unknown significance of EGF-stimulated release of SHCBP1 but more importantly also uncovered a new mode of crosstalk between the EGFR and β-catenin pathways and a novel mechanism involved in EGFR regulation of cancer cell stemness." (PMID 30177836, 2019). "While EGF-induced cancer cell migration was reduced upon AMPK knockdown, restoration of Myr-Akt or Skp2 S256D, but not Skp2 S256A, in AMPK knockdown cancer cells rescued such defect (k and Supplementary 6l)." (PMID 30413706, 2018). "Although EMT/MET conversion activates cancer related signaling pathway, transient exposure to TGF-β1 or EGF does not induce malignant proliferation of hepatic oval cells." (PMID 26955393, 2016). "Cancer cell proliferation was affected by overexpression of SLC3A2-NRG1 in the HEK 293T cells, but not by expression of SLC3A2-NRG1Δ EGF." (PMID 27626312, 2016). "Particularly, Gli-proteins are activated by EGF, K-RAS or mTOR in the absence of sonic hedgehog ligands and interact with the TGF-β signaling pathway in various malignant tumors." (PMID 27918595, 2016). "Further, EGF also has been reported to induce EMT in some cancer cell lines, but enhanced expression of MSC-related antigens in hAEC occur in cultures without addition of EGF." (PMID 22073147, 2011). "Even though deletions in chromosome 4 is a common feature in CRC, and known cancer genes such as KIT, EGF and FGF2 are situated here, none has yet been verified as predisposing for early onset or hereditary CRC." (PMID 20459617, 2010). "The expressions of mRNAs for TGF-β, acidic FGF, basic FGF and PDGF C were likewise higher in surgical cancer nodules, while that of CTGF, PDGF A and EGF were not." (PMID 15365564, 2004). "In addition, the three co-cultures expressed abundant levels of genes related to key cancer pathways, EGF and AKT/mTOR, with no obvious difference between the three cancer cell lines." (PMID 39011470, 2024). "In addition, intravenous injection of AuNP-Apt loaded with epidermal growth factor (EGF) and BIM led to targeted delivery of BIM to xenografts derived from cancer cells overexpressing EGF receptors, with no detectable systemic toxicity." (PMID 36741760, 2023). "Cancer cells evade apoptosis by increasing BCL2 expression and promoting proliferation even in the absence of growth factors, such as epidermal growth factor (EGF), by promoting mitochondrial resistance to cell membrane permeabilization." (PMID 36361782, 2022). "Although the EGF-activated PI3K/Akt/CREB signaling axis upregulates SGLT1 expression and enhances glucose uptake in intestine epithelial cells, the tyrosine kinase activity of EGFR or IGF1R and Akt signals are not needed for SGLT1 upregulation in cancer cells." (PMID 34155348, 2021). "It is tempting to speculate that certain pathophysiological conditions (e.g., carcinoma) may dissociate calmodulin from KSR1, enabling KSR1 to scaffold and activate MAPK in the absence of EGF or possibly other activators." (PMID 33766558, 2021). "To further validate the pathological implications of HSP70 phosphorylation in cancer cells, we analyzed the basic phosphorylation of HSP70 in the absence of EGF signaling in normal and cancerous lung cells harboring mutations in EGFR or K-Ras, which is a well-studied activator of ERK28." (PMID 31558706, 2019). "The anti-cancer agents of ErbB inhibitors namely, ZD1839, PD153035 and OSI-774, all ameliorate the deficits of acoustic prepulse inhibition in the animal models established by neonatal EGF injection and hippocampal lesion without apparent adverse influence." (PMID 31371697, 2019). "Therefore, amphiregulin interaction with the receptor is less efficient than EGF or TGF alpha at negative feedback mechanisms such as downregulation and degradation of the receptor, so this is advantageous for cancer growth." (PMID 29682205, 2018).
cancer (continued). "EGF treatment also did not foster the formation of EpICD in whole-cell lysates or in cytoplasmic and nuclear extracts of Kyse30 and HCT8 cells, so we conclude that EGFR-dependent RIP of EpCAM is not a common process in carcinoma cells." (PMID 30261040, 2018). "In addition to CSF1, IL-4 from CD4+ T cells is necessary to activate TAMs to produce EGF and without CD4+ T cells, TAMs are unable to induce cancer cell migration and metastasis." (PMID 29220404, 2017). "Cancer cell migration induced by the SLC3A2-NRG1 fusion protein was due to an increase in pFAK and pSrc by the SLC3A2-NRG1 fusion protein; this was not induced by SLC3A2-NRG1Δ EGF." (PMID 27626312, 2016). "EGF or HB-EGF have also been conjugated to other toxin fragments, with EGF-PE, EGF-ricin, EGF-saporin, and HBEGF-saporin also showing specific toxicity to EGFR-expressing cancers in vitro or in vivo while remaining mostly non-toxic to healthy cells." (PMID 27153091, 2016). "Interestingly, serum induced the migration of the cancer cells, but not MCF10A, suggesting that the former have acquired the ability to migrate in response to factors other than EGF that are present in the serum." (PMID 26166433, 2015). "However, why EGF and bFGF activate the CREB pathway only in a specific subset of CSC-like UM1 cells but not the other non-CSC cancer cells remains to be further elucidated." (PMID 24423398, 2013). "Moreover, in cells expressing the cancer-derived K57N mutant (termed K57N cells), MEK1(K57N), ERK, and rpS6 were persistently phosphorylated and therefore Egr1 was constitutively expressed irrespective of EGF stimulation." (PMID 35831322, 2022). "Considering that WNT7A could regulate cancer progression through canonical or non-canonical Wnt signaling, our subsequent studies were focused on the downstream signaling of WNT7A in response to EGF stimulation." (PMID 32174831, 2020). "Moreover, while considering its reported activity in EGF shedding, we specifically analyzed EGFR activation in cells overexpressing RHBDL2, but could not confirm this mechanism in our cancer cell models." (PMID 31783481, 2019). "An increased level of FSH as well as the absence of estradiol induces the higher epidermal growth factor (EGFR) mRNA expression; elevated EGFR activity initiates the DNA synthesis and cell proliferation by converging with the estrogen receptors, resulting in the development of cancer." (PMID 28356910, 2017). "We discovered that decorin evoked growth inhibition in vitro, enhanced apoptosis and blocked EGF- and FGF-mediated evasion from Matrigel (not shown), indicating that decorin exerts similar inhibitory activity on EGFR and Met dependent pathways as shown for other carcinoma cells." (PMID 23029096, 2012). "It has been known for over a decade that exogenous EGF stimulates PTHrP gene expression in a human lung SCC and keratinocyte lines, but it has not been determined whether EGFR signalling contributes to cancer-mediated syndromes such as HHM." (PMID 17533397, 2007).
infection (135 papers, 2006 to 2025). The state of being infected such as from the introduction of a foreign agent such as serum, vaccine, antigenic substance or organism. "The increment of EGF expression occurred as a response to the increase in cell damage at the site of infection or damage caused by H. pylori." (PMID 39857676, 2025). "Concerning wound colonization by P. aeruginosa, in a prior study, the authors analyzed the effects of EGF on intralesional wound healing, focusing on risk factors for infection by this microorganism." (PMID 36826286, 2023). "We demonstrated 1) lower cytokine responses in RV‐HBoV1 infection compared to sole RV infection during the acute illness, and the convalescent phase; and 2) that increased levels of EGF and MIP‐1b were associated with less severe disease in the RV‐HBoV1 group." (PMID 38006383, 2023). "HB-EGF is among the markers of angiogenesis and growth factor; therefore, it is inferred that the change in EGF is closely linked to the change in angiogenesis as part of the process that leads to the severity of the infection." (PMID 36163447, 2022). "Higher induction of TGFβ1 are more associated with active disease (infection and failure or relapses after treatment) while the higher levels of EGF are associated with adequate response to treatment." (PMID 30333964, 2018). "Ad-PKG II infection and incubating with 8-pCPT-cGMP efficiently reversed the anti-apoptotic effect of EGF and caused a significant increase in the apoptosis of the AGS cells." (PMID 24273605, 2013). "Consequently, the discussed study found that EGF from early lactation interacts with EGF receptors and decreases the formation of goblin cell passages that protect against upcoming infections, especially on pathogenic E. coli, in early life." (PMID 38534686, 2024). "EGF gene is the growth factor of pathogenic mycobacteria in granuloma tissue and macrophages, and may improve the growth rate of intracellular and extracellular mycobacteria at the infection site." (PMID 36793717, 2023). "Infection-associated induction of known inducers of myofibroblast differentiation (e.g. IL-6, IL-8, IL-11, EGF, and CTGF) may facilitate scarring in a paracrine fashion, by inducing myofibroblast differentiation or by sensitizing tissue-resident fibroblasts to pro-fibrotic stimuli." (PMID 37265500, 2023). "Thus, EIEC induced an increase of 50% of ERK1/2 phosphorylation at 0.5 h and lower than 20% at 1 and 2 h but 75% at 4 h of infection, while co-stimulation with EGF after infection, only caused an increase in about 50% at 0.5 and 1 h, and 60 and 70% at 2 h and 4 h, respectively." (PMID 27774437, 2016). "Infection with GB112 resulted in elevated production of EGF, IL-1α, IL-10, sCD40L, and fractalkine in the maternal and fetal chambers of the organ-on-a-chip models, but not in the primary human gestational membranes." (PMID 41277827, 2025). "HV-HP infection attenuated the effect of EGF treatment on ERBB2 expression in N87 cells only (p<0.05)." (PMID 40642068, 2025). "Intriguingly, an observed decrease in total EGFR levels upon WT-VACV infection or VGF/EGF treatment warrants further investigation." (PMID 39817770, 2025). "Consistent with this, we observed decreased Akt phosphorylation in response to EGF stimulation during infection of fibroblasts and hESC-derived CD34+ HPCs with WT HCMV." (PMID 39661658, 2024). "Consistent with our findings in Ripk1kd mice, mice that received EGF displayed higher peak parasite burden and an approximately twofold higher overall infection when measuring the area under the curve (P < 0.01)." (PMID 38995074, 2024). "As it prevents further fatal infection and bacterial spread, EGF’s role can be registered as an antibacterial activity." (PMID 38534686, 2024). "Next, Ifnγ−/− mice were infected with C. parvum expressing the nLuc reporter and injected intraperitoneally with PBS or 10 μg EGF on days −1, 2, and 5 of infection and every fifth day thereafter." (PMID 38995074, 2024).